MAGEA12 (MAGE family member A12)
Description:
Not known, though may play a role tumor transformation or progression. In vitro promotes cell viability in melanoma cell lines.
Synonyms: CT1.12; MAGE12
Tractability: PROTAC: ubiquitination databases record sites on it.
Gene: Protein-coding gene on chromosome X (152,733,757 to 152,737,679, forward strand). Ensembl gene ENSG00000213401.
Gene Ontology:
Molecular function: protein binding; histone deacetylase binding
Biological process: negative regulation of transcription by RNA polymerase II
Cellular component: nucleus
Homologues: Orthologues: chimpanzee MAGEA12 (99% identical), mouse Magea13 (37% identical), rat Magea13 (36% identical), zebrafish ndnl2 (19% identical), Drosophila melanogaster MAGE (15% identical). Paralogues in human: MAGEA2 (88% identical), MAGEA2B (88% identical), MAGEA3 (85% identical), MAGEA6 (84% identical), MAGEA4 (68% identical), MAGEA1 (67% identical), MAGEA8 (65% identical), MAGEA11 (60% identical), MAGEA9 (59% identical), MAGEA9B (59% identical), MAGEA10 (52% identical), MAGEB16 (42% identical), and 25 more.
Diseases named in the same sentence as MAGEA12 in open-access papers:
MAGEA12 is named in the same sentence as 25 diseases in open-access papers, as found by Europe PMC text mining. Sharing a sentence is not in itself a finding about the gene and the disease. The quoted sentences say what the papers report.
breast carcinoma (6 papers, 2011 to 2023). "In the present study, we detected 382 MAGEA12 signature genes through transcriptome analyses and showed that these signature genes are associated with the malignancy and aggressiveness of breast cancer cells." (PMID 34202157, 2021). "In this study, we present a new approach to classifying molecular breast cancer subtypes: it is based on changes in histone modifications in the promoter region of the MAGEA12 locus, which we found related closely to MAGEA12 expression and MAGEA12-associated malignancy of breast cancer cells." (PMID 34202157, 2021). "Interestingly, given that both PTN and MAGEA12 are strongly associated with mammary tumor progression, our findings also suggest that PAD2 may play a role in breast cancer development." (PMID 22911765, 2012). "It had higher levels of the active markers H3K4me3, H3K27ac, and H3K79me2 in the MAGEA12-high breast cancer cell lines." (PMID 34202157, 2021). "We also conducted an overall survival analysis of 986 breast cancer patients in the TCGA database whose MAGEA12 and MAGEA3 expression in their tumors had been measured." (PMID 34202157, 2021). "In breast cancer cell lines that had high levels of MAGEA12 expression, the promoters of the MAGEA12 signature genes were enriched for H3K4me3." (PMID 34202157, 2021). "Taken together, these results suggest that MAGEA12 regulates the expression of its target genes in breast cancer cells by inducing histone modifications." (PMID 34202157, 2021). "In this study, we analyzed the RNA-sequencing (RNA-seq) data of 70 breast cancer cell lines and found that MAGEA12 and MAGEA3 were highly expressed in a subset of these lines." (PMID 34202157, 2021). "Significantly, we also observed that breast cancer patients with high MAGEA12 and MAGEA3 expression had a poor prognosis." (PMID 34202157, 2021). "In this study, we provided evidence that suggests MAGEA12 expression and histone alteration of its locus in the genome are aggressiveness-related markers in breast cancer." (PMID 34202157, 2021). "We also found that MAGEA12 levels correlated with changes in breast cancer cell motility and invasion in monolayer cultures as well as the formation of cancer stem cell-like tumorspheres under 3D culture conditions." (PMID 34202157, 2021). "The RNA-seq data also indicated that the most highly expressed MAGE-A isoform in breast cancer cell lines was MAGEA12, followed by MAGEA3." (PMID 34202157, 2021). "High expression of MAGEA12, a member of oncogenic MAGE family, was shown to be associated with bladder carcinoma, melanoma, breast cancer and oral squamous cell carcinoma." (PMID 23950870, 2013). "MAGEA2, MAGEA3, MAGEA4, MAGEA6, and MAGEA12 are up-regulated in the CDKN2A alteration group, amongst which MAGEA3 (HR=1.61[1.27-2.04], p=8.2e-5), MAGEA4 (HR=1.38[1.08-1.77], p=0.011), and MAGEA12 (HR=1.65[1.10-2.48], p=0.015) are accompanied by worse prognosis in breast cancer." (PMID 37857018, 2023). "Taken together, these results support the notion that increased expression of MAGEA12 may contribute to the aggressiveness of breast cancer cells." (PMID 34202157, 2021). "We then asked whether the putative MAGEA12-regulated genes contributed to the characteristics of breast cancer cells by analyzing the proliferation, invasion, and migration of the MAGEA12-knockdown breast cancer cells." (PMID 34202157, 2021). "This suggests that MAGEA12 affects cell–cell adhesion and thus may be involved in the aggressiveness of breast cancer cells." (PMID 34202157, 2021). "Our findings suggest that MAGEA12 may collaborate with FOXA1 to regulate the aggressiveness of breast cancer cells." (PMID 34202157, 2021). "In conclusion, we found that MAGEA12 is associated significantly with aggressiveness in breast cancer regardless of the hormone receptor subtype status." (PMID 34202157, 2021).
breast carcinoma (continued). "In addition, we showed that MAGEA12 silencing reduced breast cancer aggressiveness by using a 3D culture system that can identify aggressive characteristics based on a cell shape classification." (PMID 34202157, 2021). "Furthermore, our gain-of-function experiments showed that MAGEA12 overexpression promoted aggressive behaviors of malignant breast cancer cells, including enhancing their cell migration and invasion." (PMID 34202157, 2021). "Overall, 19 breast cancer cell lines expressed MAGEA12, and 13 of these also expressed MAGEA3." (PMID 34202157, 2021). "Taken together, our findings suggest that MAGEA12 could be a promising therapeutic target in breast cancer, and its overexpression and epigenetic changes could serve as subtype classification biomarkers." (PMID 34202157, 2021). "Thus, in a subset of breast cancer cell lines, the 34 leading-edge genes may be regulated in a MAGEA12-independent manner." (PMID 34202157, 2021). "To explore the function of MAGEA12 in breast cancer, we used small interfering RNA (siRNA) specific for this gene (siMAGEA12) to suppress the endogenous MAGEA12 expression in the cell lines that expressed MAGEA12 at high levels (i.e., MDAMB468 and SKBR3) and then subjected these cells to RNA-seq." (PMID 34202157, 2021). "MAGEA12 and MAGEA3 were the predominant isoforms that were expressed by breast cancer cells; their expression levels were also high compared with those of other genes belonging to the MAGE-A family." (PMID 34202157, 2021). "Thus, MAGEA12 may play an important role in breast cancer malignancy." (PMID 34202157, 2021). "Consistent with this, we found that MAGEA12 and MAGEA3 expression was strongly correlated in breast cancer." (PMID 34202157, 2021). "However, the relevant functions of MAGEA12 in breast cancer remain unclear." (PMID 34202157, 2021). "MAGEA12 is reported to promote the expression of MAGEA2 and MAGEA3; The higher expression of MAGEA3 is reported to be accompanied by up-regulated expression and activity of ERα, which further leads tamoxifen resistance in breast cancer." (PMID 37857018, 2023). "However, a subset of breast cancer cell lines, including MDAMB468 and SKBR3, expressed both MAGEA12 and MAGEA3." (PMID 34202157, 2021). "Therefore, our findings raise the possibility that PAD2-mediated citrullination of the histone H3 tail at MAGEA12, PTN, and likely other promoters, plays a role in breast cancer cell proliferation." (PMID 22911765, 2012). "Thus, our data suggest that the aberrant expression of MAGEA12 and MAGEA3 genes may be useful for classifying and predicting malignant breast cancer phenotypes." (PMID 34202157, 2021). "Therefore, we propose that monitoring the expression of both MAGEA12 and MAGEA3 may help predict the prognosis and malignancy of breast cancer better than the expression of other members of the MAGE-A family genes." (PMID 34202157, 2021). "To confirm that MAGEA12 functions relate to breast cancer aggressiveness, we induced MDAMB231 and MCF7 cells, which do not express MAGEA12, to stably overexpress MAGEA12." (PMID 34202157, 2021).
colorectal cancer (3 papers, 2013 to 2021). A primary or metastatic malignant neoplasm that affects the colon or rectum. "MAGEA12 has been linked to the development or progression of prostatic carcinoma and colorectal cancer, as well as OSCC, gastric cancer, and lung cancer." (PMID 34085601, 2021).
bladder cancer (2 papers, 2013 to 2024). "A data analysis of bladder cancer patients further uncovers the possibilities of utilizing MAGEA2, MAGEA3, MAGEA4, MAGEA6, MAGEA10, MAGEA11, and MAGEA12 members as diagnostic biomarkers for bladder cancer." (PMID 38254738, 2024). "Interestingly, MAGEA2, MAGEA3, MAGEA4, MAGEA6, MAGEA10, MAGEA11, and MAGEA12 exhibited significant differences in their expression in bladder cancer compared to normal bladder samples." (PMID 38254738, 2024). "It was found that frequencies of genomic alterations among MAGEA family members in bladder cancer were MAGEA1 1.8%, MAGEA2 1.6%, MAGEA3 1.9%, MAGEA4 1.6%, MAGEA6 2.6%, MAGEA8 1.7%, MAGEA10 2%, MAGEA11, 2.1%, and MAGEA12 2.4%." (PMID 38254738, 2024).
liver cancer (2 papers, 2021). An epithelial or non-epithelial malignant neoplasm that arises from the liver. "Besides, DNA hypomethylation of MAGEA12 has been identified as a candidate biomarker for liver cancer diagnosis and prognosis." (PMID 35126454, 2021). "Similarly, in 28 cancer cell lines that exhibit p53TC and p53TI signature (that includes cells from liver cancer and other cancer types) had relatively similar levels of C19MC miRNA expression, however, the MAGEA-3, MAGEA-6 and MAGEA-12 mRNAs were selectively upregulated in p53TI subset." (PMID 34135394, 2021).
prostate carcinoma (2 papers, 2017 to 2021). A carcinoma that arises from epithelial cells of the prostate gland. "MAGEA12 down-regulates tumor suppressor p21 and thereby promotes proliferation of primary prostatic carcinoma, and it also appears to act as an oncoprotein in other types of cancer." (PMID 34085601, 2021).
thyroid cancer (1 paper, 2012). "We found the most highly down-regulated gene in the PAD2-depleted cells to be melanoma associated antigen A12 (MAGEA12), a member of the large MAGE family of proteins that have been observed in brain, liver, lung, prostate, ovarian, skin and thyroid cancers." (PMID 22911765, 2012).
cancer (24 papers, 2012 to 2025). A tumor composed of atypical neoplastic, often pleomorphic cells that invade other tissues. "We first compared gene expression between recurrent and nonrecurrent cases, and we found that recurrence was associated with higher expression of cancer/testis antigen (CTA) genes including MAGEA12, GAGE1, and GAGE2C as well as with lower expression of GZMK." (PMID 37402831, 2023). "We have excluded the least cancer-associated CTA genes: Magea12, Magea9b, Oip5 and Casc5." (PMID 41009820, 2025). "Fifth, the genes were previously associated with human cancers, in particular MAGEA12 however only DISCS LARGE (DROSOPHILA) HOMOLOG-ASSOCIATED PROTEIN 5 (DLGAP5) and MATRIX METALLOPEPTIDASE 1 (MMP1) have been previously reported to be up-regulated in HCC tumors." (PMID 23950870, 2013). "A general dose- and time-dependent cytotoxic effect also widely emerged (IC50 values ranging from 50 to 300 μM) via the downregulation of the MAGEA12 pathway, which, when activated, led to promoted cancer cell viability." (PMID 36678905, 2023). "MAGEA12 was shown before to be repressed in normal cells by promoter methylation and activated in cancer cells by demethylation, whereas the role of GPM6B and FCRL1 methylation in promoter activity was not previously tested." (PMID 23950870, 2013). "Differential methylation of promoters of these genes was not previously reported in cancer although methylation-dependent regulation of MAGEA12 promoter was shown in several cancer cell lines." (PMID 23950870, 2013). "A probe within MAGEA12 should be used in combination with GPM6B in order to detect cancer as melting curves for tumors of a few patients with PVTT overlap with NorAdjRef curve." (PMID 23950870, 2013). "We used MAGEA12 as an additional “negative” control because MAGEA12 is a cancer-testis antigen and the expression of MAGEA12 causes increases in cell proliferation; furthermore, MAGEA12 shares only 39% sequence identity with MAGEB2." (PMID 40141091, 2025). "Thus, the Akt inhibitor MK-2206 was used to incubate the cancer cells transfected with MAGEA12 plasmid." (PMID 34085601, 2021). "How MAGEA12 may promote tumor progression in cancers such as OSCC is unclear." (PMID 34085601, 2021). "As demonstrated by others, we found using Pearson correlation test that SS and MRCL highly express cancer–testis (CT) antigens, specifically MAGEA3/A6 and MAGEA12." (PMID 35267598, 2022). "Next, we examined the expression of MAGEA12 and MAGEA3 in normal tissues and various cancer cell lines by using genotype-tissue expression (GTEx) and Cancer Cell Line Encyclopedia (CCLE), respectively." (PMID 34202157, 2021). "Two genes (MAGEA12, TRPC7) are up-regulated and one gene (FCGRT) is down-regulated in the metastases from the 4 cancer types with significant gene lists." (PMID 29254233, 2017). "The probes correspond to three genes GPM6B, MAGEA12, and FCRL1 that were overexpressed and demethylated in our set of HCC patients and up-regulated in many other types of cancer." (PMID 23950870, 2013). "Shared overexpression was found only for cancer-germline antigens CT83, MAGEA12 and XAGEA1." (PMID 40165973, 2025). "The OSCC-related cancer cell lines used in the reported studies were as follows: PE/CA-PJ15; SCC-VII; SCC-25; SCC-15; YD-10B; YD-9; YD-38; KB; SAS; Sa3; HSC-3; FaDU; Ca9-22; Cal-27; Cal-27-overexpressing MAGEA12; and cisplatin-resistant Cal-27." (PMID 36678905, 2023). "In addition to the KRAS and SALL4oncogenes, CGS4 tumors highly express cancer-testis antigens (CTAs) such as MAGEA3 and MAGEA12, indicating that they might be good candidates for testing CTA-mediated cancer vaccine therapy." (PMID 37674200, 2023). "Similarly, expression of MAGEA3, MAGEA6 and MAGEA12 was greater than 3-fold in all cancer lines, regardless of origin, when compared to HEK cells." (PMID 32760472, 2020).
tumor (19 papers, 2009 to 2025). "Melanoma-associated antigen 12 (MAGEA12) is also highly expressed in some tumor cells and has been found to exert oncogenic role by promoting the ubiquitination and degradation of the tumor suppressor p21." (PMID 35126454, 2021). "MAGEA12 is a member of the human MAGE gene family, primarily encoding tumor-associated antigens recognized by various allelic forms of MHC class I molecules on the surface of tumor cells, recognized by cytotoxic T lymphocytes (CTLs)." (PMID 39883700, 2025). "Temperature values of melting curve peaks of GPM6B (A), MAGEA12 (B) and FCRL1 (C) amplicons in tumor samples and normal liver tissues in Chinese (Ch) and Bangladeshi (B) cohorts as analyzed by HRM." (PMID 23950870, 2013). "Significant tumor-specific demethylation was found in MAGEA3 (p<0.005), MAGEA12 (p<0.025), MAGEA4 (p<0.018), MAGEA1 (p<0.001), TKTL1 (p<0.025) and MAGEA5 (p<0.007)." (PMID 19997593, 2009). "Unlike the TCGA results, MAGEA12 showed no expression difference between normal and tumor samples in the GEO dataset, while the analysis results of the other genes were consistent with those of the TCGA database." (PMID 39883700, 2025). "The results showed that, in the TCGA cohort, C12orf56 and RORC had higher expression in normal samples, while EREG, INHBB, MAGEA12, and MMP10 had higher expression in tumor samples; ASRGL1 showed no expression difference between normal and tumor samples." (PMID 39883700, 2025).
MAGEA12 also shares sentences with these, for which no sentence is quoted: melanoma (4 papers); ovarian carcinoma (3); gastric cancer (2); lung carcinoma (2); oral squamous cell carcinoma (2); brain tumors (1); chronic hepatitis B infection (1); cutaneous squamous cell carcinoma (1); invasive breast carcinoma (1); leukemia (1); lymphoid leukemia (1); metastatic melanoma (1); pancreatic cancer (1); sarcoma (1); serous ovarian cancer (1); testicular cancer (1); uterine sarcoma (1).